MEFV (MEFV innate immunity regulator, pyrin)
Diseases named in the same sentence as MEFV in open-access papers (continued):
Sharing a sentence is not in itself a finding about the gene and the disease.
familial Mediterranean fever (continued). "Familial Mediterranean Fever (FMF) is a monogenic autoinflammatory disease, secondary to mutations of MEFV gene in the chromosome 16p13, and typically characterized by recurrent self-limiting attacks of fever, arthritis, aphthous changes in lips and/or oral mucosa, erythema, serositis." (PMID 31443670, 2019). "Finally, Takata-MGLs were utilized in the original study to investigate the effect of a familial Mediterranean fever (FMF), causing MEFV-mutation on morphological features and functions of MGLs." (PMID 31856864, 2019). "Familial Mediterranean fever is an autoinflammatory disease of unknown etiology, characterized clinically by recurrent attacks of sudden-onset fever with arthralgia and/or thoracoabdominal pain and pathogenetically by autosomal recessive inheritance due to a mutation in the MEFV gene." (PMID 29490685, 2018). "Familial Mediterranean fever (FMF) is an ethnically restricted autosomal recessive disease, usually caused by loss-of-function mutations in the MEFV gene on the short arm of chromosome 16." (PMID 29490685, 2018). "In familial Mediterranean fever, analyses of the MEFV gene should be performed in potential live kidney donors from a direct family member (either between siblings or between parents and children)." (PMID 28859624, 2017). "Familial Mediterranean fever (FMF, OMIM #249100) is an autosomal recessive disorder caused by gain-of-function mutations in the MEFV gene encoding pyrin." (PMID 28588486, 2017). "Familial Mediterranean Fever (FMF) is the most common of AIDs, transmitted as an autosomal recessive pattern, and is caused by mutations in the Mediterranean fever (MEFV) gene, which encodes the protein pyrin and is located on the short arm of the 16th chromosome." (PMID 32185281, 2017). "The MEFV gene is also responsible for familial Mediterranean fever, which is an autosomal recessive disorder." (PMID 28499374, 2017). "Familial Mediterranean fever (FMF) is a genetic auto-inflammatory disease characterized by self-limiting relapsing fever and polyserositis, caused by mutations of the MEFV gene encoding pyrin." (PMID 27026266, 2016). "Several studies have identified an association between Behçet’s disease (BD) and mutations in the Mediterranean fever (MEFV) gene, which was originally linked to the autosomal recessive disease, Familial Mediterranean fever." (PMID 26176758, 2015). "Another intriguing finding is the identification of the gene MEFV responsible for the most common inheritable fever syndrome, familial Mediterranean fever (characterized by recurrent fever and inflammation)." (PMID 23658707, 2013). "The most common of these diseases, familial Mediterranean fever (FMF), is caused by mutations in the MEFV locus, which encodes the protein pyrin." (PMID 19584923, 2009). "The gene for Familial Mediterranean Fever (MEFV) is expressed in early leukocyte development and is regulated in response to inflammatory mediators." (PMID 19624813, 2009). "Pyrin was named after the Greek word for fever, Pyretós, owing to the association between MEFV variants and familial Mediterranean fever (FMF), the most common noninfectious genetic fever in the world." (PMID 41062723, 2025). "In addition, we have a sibling pair and a singleton with PANS who have been diagnosed with Familial Mediterranean Fever (FMF), each of whom carries variants in the MEFV gene associated with this condition (R202Q and A744S, unpublished observations)." (PMID 40894167, 2025). "Despite the high carrier frequency of Familial Mediterranean Fever in the Turkish population, no variants in the MEFV gene were observed in our study in Northern Cyprus." (PMID 37895316, 2023). "Misdiagnosis of familial Mediterranean fever is common in endemic countries due to the reliance on clinical symptoms without analysis of the mutations in the MEFV genes particularly, before 1997." (PMID 35145669, 2022).
familial Mediterranean fever (continued). "Although a second variant was not identified in MEFV, the highly penetrant M680I mutation has been previously observed in symptomatic carriers of familial Mediterranean fever (FMF, OMIM 249100)." (PMID 35743704, 2022). "This study shows that MEFV mutations that cause familial Mediterranean fever enable pyrin activation in the absence of prior licensing." (PMID 36342970, 2022). "In many patients there is no genetic confirmation of the disease; furthermore, some subjects with the relieve of MEFV mutations, show a phenotype not in line with the diagnosis of Familial Mediterranean Fever." (PMID 31941537, 2020). "Familial Mediterranean fever (FMF) is one of the paradigmatic hereditary autoinflammatory disorders, caused by point mutations, either non-sense or missense, in the Mediterranean fever (MEFV) gene, generally inherited in an autosomal recessive way." (PMID 31849945, 2019). "Examples are MEFV/pyrin in familial Mediterranean fever (FMF), TNFRSF1A/TNF receptor type 1 in TNF receptor-associated periodic syndrome (TRAPS), and nucleotide-binding domain, leucine-rich-containing family, pyrin domain-containing 3 (NLRP3) in cryopyrin-associated periodic syndromes (CAPS)." (PMID 28421072, 2017). "MEFV was originally identified as a candidate gene for familial Mediterranean fever." (PMID 28800602, 2017). "Familial Mediterranean fever has long being considered as an autosomal recessive disease caused by mutations in the MEFV gene, which is composed of 10 exons and encodes a 781 amino acids protein called pyrin or marenostrin or TRIM20." (PMID 27066000, 2016). "Familial Mediterranean Fever (FMF), characterized by recurrent fever and inflammation of serous membranes, is an autosomal recessive disease caused by mutations in the Mediterranean fever (MEFV) gene." (PMID 24980720, 2014). "The clinical profile of familial Mediterranean fever (FMF) may be influenced by MEFV allelic heterogeneity and other genetic and/or environmental factors." (PMID 23437051, 2013). "Familial Mediterranean Fever (FMF) has traditionally been considered to be an autosomal-recessive disease, however, it has been observed that substantial numbers of patients with FMF possess only 1 demonstrable MEFV mutation." (PMID 23437051, 2013). "HS may affect patients with familial Mediterranean fever (FMF), a prototypic monogenic AID, carrying MEFV mutations, with a higher frequency of MEFV mutations reported in HS patients than in healthy controls, suggesting a potential contribution to HS pathogenesis." (PMID 39274425, 2024). "In 1997, the familial Mediterranean fever gene (MEFV gene) located on the short arm of chromosome 16 was identified to be responsible for FMF." (PMID 37206860, 2024). "We sought to investigate the role of epigenetic modifications beside genetic alterations in the MEFV gene in familial Mediterranean fever (FMF)." (PMID 36661534, 2023). "Familial Mediterranean fever (FMF) is the prototype of a HRF and is caused by gain-of-function mutations of the MEFV gene, coding for pyrin." (PMID 35812440, 2022). "Familial Mediterranean fever (FMF; MIM: 249100) is classically regarded as an autosomal recessive disease caused by variants in MEFV, but one mutant allele is sufficient to cause subclinical systemic inflammation." (PMID 35126383, 2021). "The prototypical inflammasomopathy with periodic fever is familial mediterranean fever (FMF), a disease caused by mutations in the MEFV (mediterranean fever) gene encoding the protein PYRIN, which is part of the inflammasome complex." (PMID 34066649, 2021). "The Mediterranean fever (MEFV) gene is located on the short arm of chromosome 16 and is known to be responsible for familial Mediterranean fever (FMF)." (PMID 28800602, 2017). "We report on a familial Mediterranean fever (FMF) patient homozygous for p.M694V in the MEFV gene who developed chronic myelomonocytic leukemia (CMML) leading to an uncontrolled and fatal inflammatory syndrome." (PMID 26076658, 2015).
familial Mediterranean fever (continued). "Familial Mediterranean fever (FMF) is the most common AID, predominating in people living around the Eastern Mediterranean basin and is caused by loss-of-function mutations within the MEFV gene: pyrin is the product of MEFV and is an intracellular regulator of IL-1 production." (PMID 23971037, 2013). "The same principle applies to other genes: ATP13A2 responsible for a juvenile onset of PD, GBA responsible for Gaucher’s disease, ABCA1 responsible for Tangier disease, and MEFV responsible for familial Mediterranean fever (FMF)." (PMID 23970884, 2013). "Mutations in the MEFV gene, which encodes the protein named pyrin (also called marenostrin or TRIM20), are associated with the autoinflammatory disease familial Mediterranean fever (FMF)." (PMID 27066000, 2016). "At the same time, the advantage in accuracy is absolutely overwhelming for the genes GATA2, MEFV, and NLRP3, which relate with IMD21 (immunodeficiency 21, monocytopenia and mycobacterial infection syndrome), Familial mediterranean fever, and Familial cold autoinflammatory syndrome, respectively." (PMID 39975544, 2025). "Protracted febrile myalgia (PFM) is a severe form of myalgia typically occurring in patients with familial Mediterranean fever (FMF), a monogenic autoinflammatory disease caused by mutations in the MEFV gene, with a classical, although not constant, autosomal recessive inheritance." (PMID 39768554, 2024). "We did not consider Familial Mediterranean Fever and the MEFV gene for the analysis, since an earlier work from our group comprehensively analyzed the genetic epidemiology of the genetic variants for this gene." (PMID 34054914, 2021). "No mutation was detected in MEFV, a gene responsible for familial Mediterranean fever (FMF)." (PMID 22940910, 2013). "Since the discovery in 1997 of the first gene MEFV (Mediterranean fever (MIM 608107)), responsible for familial Mediterranean fever (FMF), more than 40 new known genetically defined AIDs have been identified, notably by high-throughput sequencing approaches." (PMID 31635385, 2019). "Familial Mediterranean fever (FMF) gene analysis was negative in all patients except for one, who had a heterozygous MEFV gene defect (M694V)." (PMID 40266382, 2025). "Recently, three related subjects with homozygous mutations for MEFV p.S208C and TRAP1 p.R128H presented with familial Mediterranean fever (FMF) with no reported opportunistic infection." (PMID 39224595, 2024).
Mediterranean fever (47 papers, 2009 to 2025). "MEditerranean FeVer (MEFV) gene analysis revealed exon 10 mutations (p.Met694Ile), resulting in an FMF diagnosis." (PMID 39391461, 2024). "The penetrance of MEFV pathogenic variants is complex, ranging from asymptomatic heterozygotes to heterozygotes with a clinical manifestation of Mediterranean fever." (PMID 39062917, 2024). "The gene responsible for FMF, MEFV (MEditerranean Fever), is composed of 10 exons on chromosome 16p13.3 and encodes pyrin (or marenostrin) protein which is a component of IL-1 inflammasome pathway, hence regulates IL-1ß processing and activation." (PMID 35573950, 2022). "We evaluated the performance of latest Nanopore sequencing in combination with a dedicated data-analysis pipeline for single nucleotide polymorphism (SNP) genotyping of the familial Mediterranean fever gene (MEFV) by amplicon sequencing of 47 clinical samples." (PMID 35298548, 2022). "We aimed to compare early markers of endothelial dysfunction and atherosclerosis in FMF-AA with a homozygous M694V mutation (Group 1 = 76 patients) in the Mediterranean fever (MEFV) gene and in patients with other genotypes (Group 2 = 93 patients)." (PMID 35629299, 2022). "Mutations in the Mediterranean fever (MEFV) gene, which encodes the pyrin protein, are responsible for the pathogenesis of FMF." (PMID 36134042, 2022). "Mutations in the MEFV gene are highly prevalent in the Middle East and Mediterranean countries where brucellosis is endemic." (PMID 35979363, 2022). "TRIM20, encoded by the MEFV gene, a known risk locus for the autoinflammatory disease Familial Mediterranean Fever." (PMID 37425656, 2022). "Here, the frequency of Mediterranean Fever (MEFV) gene mutation and its effect on the outcome of IBD were evaluated." (PMID 34819953, 2021). "FMF is caused by the mutations in the MEFV (Mediterranean fever) gene and inherited in an autosomal recessive manner." (PMID 30887796, 2019). "FMF is linked to a mutation in the Mediterranean Fever (MEFV) gene in a region encoding the B30.2 domain of pyrin." (PMID 31118894, 2019). "FMF is caused by a number of mutations of the Mediterranean fever (MEFV) gene, coding a protein named pyrin that acts as a major regulatory component of the inflammasome." (PMID 30594222, 2018). "We recruited patients with a clinical diagnosis of FMF, one exon-10 Mediterranean fever (MEFV) gene mutation and considered resistant to colchicine, via networks of expert physicians." (PMID 28302131, 2017). "Mutations of the Mediterranean fever (MEFV) gene coding pyrin (marenostrin) protein, which is located in the short arm of the 16th chromosome (16p13.3), are responsible for the disease." (PMID 26064124, 2015). "The associated gene, MEFV (Mediterranean Fever), is expressed primarily by cells of myeloid lineage and encodes the protein pyrin/TRIM20/Marenostrin." (PMID 23226472, 2012). "For example, the vast majority of FMF-associated mutations are located in the C-terminal B30.2 (SPRY) domain of the MEFV (Mediterranean Fever) gene-encoded protein product pyrin." (PMID 19851467, 2009). "In addition, the gene which is responsible for FMF—Mediterranean fever (MEFV) gene—has been identified as a susceptibility gene for BD." (PMID 37176572, 2023). "Our data further support the hypothesis that MEFV mutations may provide an evolutionary selective advantage to confer protection against brucellosis." (PMID 35979363, 2022). "Mutations in MEFV are associated with Mediterranean fever, a hereditary periodic fever syndrome." (PMID 35298548, 2022). "One patient had an additional E148Q mutation in the MEFV gene, which is considered as VOUS for Familial Mediterranean Fever." (PMID 39025961, 2024). "Mediterranean fever (MEFV) is the gene responsible for the pathogenesis of FMF and encodes the Pyrin protein." (PMID 37370025, 2023). "Mediterranean fever was suspected and the MEFV gene (NM_000243), responsible for the disease was studied by Sanger sequencing." (PMID 36061186, 2022).
Mediterranean fever (continued). "Mutations in genes related to amyloidosis were found in 15% (n = 22) of patients, being: transthyretin (TTR) (59%; n = 13); fibrinogen (27%; n = 6); and Mediterranean Fever (MEFV) gene (14%; n = 3)." (PMID 36471404, 2022). "Genetic testing excluded Mediterranean fever and chronic atypical neutrophilic dermatosis with lipodystrophy and elevated temperature (CANDLE) syndrome caused by mutations in MEFV and PSMB8, respectively." (PMID 30804083, 2019). "It is well established that mutations in PYRIN, alternatively named MEFV, are associated with a hereditary autoinflammatory disease termed Mediterranean fever as well as severe IBDs." (PMID 30717382, 2019). "Since the discovery of the familial Mediterranean fever gene MEFV (also known as marenostrin) in 1997, 18 other genes responsible for monogenic autoinflammatory diseases have been identified to date." (PMID 24070009, 2013). "Colchicine may have anti-inflammatory effects in FMF by reorganizing the actin cytoskeleton and down regulating Mediterranean fever (MEFV) gene expression." (PMID 28302131, 2017). "Positive controls were noted to have significantly increased expression of genes associated with the inflammatory response, including CCL5 (chemokine ligand 5), MEFV (Mediterranean Fever, codes for pyrin), SLC11A (solute carrier family 11 member 2), and TNF (tumor necrosis factor) (P < .0001)." (PMID 28943993, 2017). "Here we report the investigation of the suitability of two methodologies: transient transfection and electroporation, to deliver siRNA targeted against the putative immunomodulatory gene Mediterranean fever (MEFV) into primary bovine monocyte-derived macrophages (bMDM)." (PMID 24598124, 2014). "TRIM20, known as MEFV (Mediterranean fever) protein, regulates the turnover of IκBα and interaction with NF-kB p65, and positively regulates the NF-kB pathway." (PMID 30185771, 2018).
Fever (23 papers, 2013 to 2025). Body temperature elevated above the normal range. "FMF is considered to be inherited autosomal recessive and is associated with point mutations (single substitutions) in the Mediterranean Fever (MEFV) gene." (PMID 35298548, 2022). "Human leukocyte antigen B54 has been associated with Sweet’s syndrome, aswell as heterozygous mutations in MEFV gene that is observed in familialMediterranean fever." (PMID 31845610, 2019). "The pyrin protein (also known as marenostrin; TRIM20), named after the Greek word for fever, is a 781-amino acid, ~95 kDa protein that is encoded by MEFV on chromosome 16." (PMID 31456795, 2019). "This autosomal recessive disease is caused by mutations in the Mediterranean Fever (MEFV) gene, which encodes pyrin, a key protein in innate immunity that regulates inflammatory responses in the caspase-1 and interleukin-1β pathways by suppressing inflammasome activation." (PMID 40442506, 2025). "Diagnosis is confirmed by mutation analysis of the Mediterranean Fever (MEFV) gene." (PMID 39335710, 2024). "One study on children with periodic fever and carrying MEFV mutations reported that patients with heterozygous E148Q or V726A variant less frequently experienced severe abdominal and chest attacks compared to those with heterozygous exon 10 mutations (M694V, M694I, M680I)." (PMID 33726481, 2021). "It is caused by mutations in Mediterranean fever (MEFV) gene that encodes protein pyrin (TRIM20)." (PMID 33163006, 2020). "Mutations in the Mediterranean fever (MEFV) gene are localized on the p arm of chromosome 16." (PMID 29735907, 2018). "The FMF gene, also called as Mediterranean Fever (MEFV) gene, was mapped to the short arm of chromosome 16." (PMID 23865042, 2013). "Suspecting Familial Mediterranean Fever molecular analysis of MEFV gene, was performed." (PMID 34078428, 2021).